CSF1R (colony stimulating factor 1 receptor)
Diseases named in the same sentence as CSF1R in open-access papers (continued):
Sharing a sentence is not in itself a finding about the gene and the disease.
Leukoencephalopathy (continued). "As there are no laboratory findings specific for CSF1R-related leukoencephalopathy, detailed clinical examinations are important to exclude differential diagnoses." (PMID 33287883, 2020). "There are no available specific therapies for CSF1R-related leukoencephalopathy to date, and development of a potential microglia-based treatment is warranted." (PMID 33287883, 2020). "To avoid further nomenclature confusion and adopting current nomenclature trends, we will use the term of CSF1R-related leukoencephalopathy, rather than HDLS or POLD, in this review." (PMID 33287883, 2020). "Although there is no sex difference in the prevalence of CSF1R-related leukoencephalopathy, it was reported that female patients develop clinical symptoms significantly earlier than do men." (PMID 33287883, 2020). "Microglial replacement, which represents a potential therapy for CSF1R-related leukoencephalopathy, has been the focal point of intense non-clinical research and may enter into clinical studies in the near future." (PMID 35185751, 2021).
Alzheimer disease (44 papers, 2015 to 2025). A progressive, neurodegenerative disease characterized by loss of function and death of nerve cells in several areas of the brain leading to loss of cognitive function such as memory and language. "In this study, we present a case of CSF1R-microglial encephalopathy in a patient with a splice mutation (c.2654 + 1G>A) in the CSF1R gene, a family history of early-onset dementia, and a CSF biomarker profile suggesting Alzheimer’s disease-related changes." (PMID 40893935, 2025). "CSF1R has been found to be increased in disease-associated microglia in the Alzheimer’s disease brain." (PMID 35743315, 2022). "The ability to deplete microglia via CSF1R inhibition, based on mouse model studies, was recently recognized as a possible therapeutic strategy for the treatment of several brain diseases associated with inflammation, including Alzheimer's disease and glioma." (PMID 34282843, 2021). "These target-directed therapeutic approaches are in line with preclinical studies demonstrating a beneficial effect of CSF1-R inhibitor-induced microglia depletion, e.g., in Alzheimer disease models and after traumatic brain injury." (PMID 37235660, 2023). "Similar to our results, the upregulation of CSF1R has been reported in the microglia of post-mortem brain samples from patients with Alzheimer’s disease (AD)." (PMID 37108258, 2023). "Several studies have identified CSF-1R as a pharmacological target for alleviating disease progression, including those of rheumatoid arthritis, Alzheimer’s disease, and cancer." (PMID 37876929, 2023). "It is now clear that depleting microglia, at least temporarily via CSF1R inhibitors, can be beneficial in mouse models of Alzheimer's disease, and therefore has clinical potential." (PMID 34282843, 2021). "Similar findings have been reported with other CSF1R inhibitors to treat models of multiple sclerosis demyelination, Alzheimer’s disease neuroinflammation and neurodegeneration." (PMID 34899694, 2021). "PLCγ2 also sits downstream of CSF1R, inhibitors or which are currently in trials in the context of Alzheimer’s disease." (PMID 34254352, 2021). "In this context, we highlight microglial TREM2 and CSF1R as emerging targets for disease-modifying therapy in Alzheimer’s disease (AD) and other neurodegenerative disorders." (PMID 33652870, 2021). "This work strongly supports the potential of inhibition of CSF1R as a target for the treatment of Alzheimer’s disease and other tau-mediated neurodegenerative diseases." (PMID 31504240, 2019). "We then moved to a more relevant model for tauopathies and Alzheimer’s disease and assessed the impact of CSF1R inhibition by JNJ-527 in P301S mice." (PMID 31504240, 2019). "Extensive studies by Green and co-workers have shown no adverse physiological or behavioral effects of short- or long-term depletion of microglia via CSF1R inhibition in acute brain injury, aging and Alzheimer’s disease mouse models." (PMID 31753024, 2019). "Overall, this work strongly supports the potential for inhibition of CSF1R as a target for the treatment of Alzheimer’s disease and other tau-mediated neurodegenerative diseases." (PMID 31504240, 2019). "We investigated the proliferative dynamics of microglial cells and the expression of the components of the CSF1R pathway in a relevant model of Alzheimer’s disease-like pathology (APPswe, PSEN1dE9; APP/PS1)." (PMID 26747862, 2016). "Our results provide a proof of efficacy of CSF1R inhibition for the blockade of microglial proliferation in a model of Alzheimer’s disease-like pathology." (PMID 26747862, 2016). "In this study we found increased proliferation of microglial cells in human Alzheimer’s disease, in line with an increased upregulation of the CSF1R-dependent pro-mitogenic cascade, correlating with disease severity." (PMID 26747862, 2016).
Alzheimer disease (continued). "In this study, we set out to define the microglial proliferative response in both human Alzheimer’s disease and a mouse model of Alzheimer’s disease-like pathology, as well as the activation of the CSF1R pathway." (PMID 26747862, 2016). "In summary, the present data provide strong evidence for an increased proliferative response in microglia in Alzheimer’s disease, as well as their dependence upon CSF1R activation." (PMID 26747862, 2016). "Our findings support the relevance of CSF1R signalling and microglial proliferation in chronic neurodegeneration and validate the evaluation of CSF1R inhibitors in clinical trials for Alzheimer’s disease." (PMID 26747862, 2016). "Olmos-Alonsoet al.show that microglial proliferation in Alzheimer’s disease tissue correlates with overactivation of the colony-stimulating factor 1 receptor (CSF1R) pathway." (PMID 26747862, 2016). "Here, we report a case of CSF1R gene mutation with Alzheimer’s disease pathological changes and negative DWI." (PMID 40893935, 2025). "Together, these findings indicate that selective CSF1R inhibition could offer therapeutic benefits through modulation of neuroinflammation and amyloid pathology in Alzheimer’s disease." (PMID 40573211, 2025). "Furthermore, the CSF1R inhibitor JNJ-527 has completed Phase 1 clinical trials for Alzheimer’s disease, although subsequent trial details remain unpublished." (PMID 40573211, 2025). "Recent studies suggest that CSF1R inhibitors may reduce amyloid plaque formation in Alzheimer’s disease models." (PMID 40573211, 2025). "Furthermore, CSF‐1R inhibitors have shown potential in reducing neuroinflammation and improving cognitive function in models of Alzheimer's disease and Parkinson's disease." (PMID 40304412, 2025). "The pharmacological inhibition of CSF1R is beneficial for subjects with Alzheimer's disease." (PMID 35187175, 2022). "Existing and emerging inhibitors of CSF1R may prevent neurodegeneration in models of Alzheimer’s disease and traumatic brain injury, which supports further research into the therapeutic potential of CSF1R antagonism in select neurologic conditions." (PMID 36175737, 2022). "CSF1R loss-of-function mutations are the major cause of adult-onset leukoencephalopathy with axonal spheroids and pigmented glia (ALSP) and its dysfunction has also been implicated in other neurodegenerative disorders including Alzheimer’s disease (AD)." (PMID 34867307, 2021). "Indeed, we have recently shown that CSF1R inhibitor-based microglial depletion prevents disease-associated PNN reductions in models of Huntington’s and Alzheimer’s disease (AD)." (PMID 34413489, 2021). "Four drugs could be used synergistically to reduce microglia-mediated inflammation in Alzheimer’s disease, through the inhibition of CSF1R and CD33." (PMID 32398742, 2020). "Overall, our study establishes the potential for clinical application of the CSF1R inhibitor JNJ-527 in Alzheimer’s disease and other neurodegenerative disorders where neuroinflammation may play a role." (PMID 31504240, 2019). "Csf1r, which was downregulated in our screen, facilitates protection and survival of uninjured neurons in the hippocampus and cortex, and Csf1r signaling via administration of Csf1 ameliorates memory deficits in an Alzheimer's disease mouse model." (PMID 30013462, 2018). "Our results provide the first proof of the efficacy of CSF1R inhibition in models of Alzheimer’s disease, and validate the application of a therapeutic strategy aimed at modifying CSF1R activation as a promising approach to tackle microglial activation and the progression of Alzheimer’s disease." (PMID 26747862, 2016). "Although these ideas would lead to the evaluation of the efficacy of CSF1R inhibitors in Alzheimer’s disease, we have little evidence regarding the level of microglial proliferation in Alzheimer’s disease or the effects of CSF1R targeting in animal models of Alzheimer’s disease-like pathology." (PMID 26747862, 2016).
Alzheimer disease (continued). "Therefore, a more targeted analysis of the peripheral effects of CSF1R inhibition in ongoing or planned clinical trials is necessary, to better ponder the long-term side effects of potential therapies for Alzheimer’s disease." (PMID 26747862, 2016). "The candidate marker proteins with the highest depletion-caused loss include junction plakoglobin (suggested as a marker of atherosclerosis), colony-stimulating factor 1 receptor (marker candidate of amyotrophic lateral sclerosis) and plasminogen (marker candidate of Alzheimer’s disease (AD))." (PMID 26471478, 2015). "The patient carries a heterozygous splice site mutation in the CSF1R gene (c.2654 + 1G>A, NM_005211.3), accompanied by progressive cognitive decline and a CSF biomarker profile suggesting Alzheimer’s disease-related changes, with no white matter abnormalities detected on the DWI sequence." (PMID 40893935, 2025). "Indeed, CSF‐1R inhibitors have been shown to mitigate neuroinflammation, enhance the survival and proliferative capabilities of microglia, and impede the advancement of Alzheimer's disease in mouse models." (PMID 40304412, 2025). "In addition, CSF biomarker profiles in patients with CSF1R-microglial encephalopathy may exhibit Alzheimer’s disease-related changes." (PMID 40893935, 2025). "CSF1R signaling is known to be important for microglial proliferation in response to stress or injury, with increased M-CSF expression observed upon in vivo LPS treatment, upon ischemic injury, in Alzheimer’s disease and its animal models, and in aged mice and human." (PMID 38576039, 2024). "CSF1R signaling plays a role in the survival, homeostatic functions, and proliferation of microglia, and its expression may be higher in the brains of patients with certain neurologic conditions such as Alzheimer’s disease or amyotrophic lateral sclerosis." (PMID 36175737, 2022). "KEGG terms of specifically upregulated genes in CSF1R monocytes in these four testudines were enriched in biological pathways for oxidative phosphorylation, disease (Parkinson’s disease, non-alcoholic fatty liver disease, Huntington’s disease, Alzheimer’s disease, etc.), and lysosomes." (PMID 36552787, 2022). "Inhibition of CSF1R signaling may provide an intervention approach or therapeutic due to the inhibition of the process of amyloid deposition formation at the very earliest stages of Alzheimer's disease." (PMID 32908485, 2020). "Interestingly, CSF1R signalling mediates microglial proliferation and survival, and both upregulation of CSF1R and increased proliferation of microglia have been reported in post-mortem samples from patients with Alzheimer’s disease." (PMID 31504240, 2019). "Even though CSFIR (colony stimulating factor 1 receptor) is a second-level interacting partner to AD known gene, based on its intrinsic neuroprotective function, it could also be a potential gene of interest in Alzheimer’s disease condition." (PMID 26784894, 2016). "A more specific approach to test the role of microglia is to deplete microglia using the colony stimulating factor 1 receptor (CSF1R) inhibitor PLX5622, which has been used to test the role of microglia in brain diseases such as Alzheimer’s disease." (PMID 39015474, 2024). "In addition, it is important to understand the systemic effects of CSF1R inhibition on macrophages, as inhibition of CSF1R is a clinical strategy for the intentional depletion of macrophages in various disease contexts, including Alzheimer’s disease, brain injury and cancer." (PMID 32367800, 2020). "The observed beneficial effects of prolonged and specific targeting of CSF1R, with the orally available inhibitor GW2580, provide a proof of target engagement and efficacy in a model of Alzheimer’s disease-like pathology." (PMID 26747862, 2016).
Alzheimer disease (continued). "With their innate physiological roles as well as being direct interacting partners (guilt-by-association) to already known AD genes (JAK2 and PECAM1) increases the chances of the two genes (CSF1R and GAB1) as novel candidate genes for Alzheimer’s disease." (PMID 26784894, 2016). "Here, we determined the dose-dependent effects of a specific CSF1R inhibitor (PLX5622) on microglia in both wild-type and the 3xTg-AD mouse model of Alzheimer’s disease." (PMID 26232154, 2015). "The CSF1R inhibitor PLX3397, an FDA-approved treatment for a rare cancer, has been shown to reduce microglia count, lower inflammation, and increase synaptic markers in mouse models of Alzheimer’s disease (AD)." (PMID 40791424, 2025). "Prolonged reduction of microglial activation and proliferation in Alzheimer’s disease mice using a selective CSF1R inhibitor prevents cognitive decline, regardless of amyloid plaque pathology." (PMID 26747862, 2016). "However, the study of microglial proliferation in Alzheimer’s disease and validation of the efficacy of CSF1R-inhibiting strategies have not yet been reported." (PMID 26747862, 2016).
Cognitive impairment (35 papers, 2015 to 2026). Abnormal cognition is characterized by deficits in thinking, reasoning, or remembering. "These Csf1rI792T/+ mice exhibit hallmark features of CSF1R-related disorder (CSF1R-RD), including cognitive deficits, ventricular enlargement, reduced microglia, axonal spheroids, and demyelination." (PMID 41763216, 2026). "Low-dose PLX5622 has been shown to prevent sepsis induced synaptic loss and cognitive impairment, underscoring the role of CSF1R signaling in inflammation related synaptic remodeling." (PMID 41292555, 2025). "For example, in two separate models of AD, the APPswe/PS1 and the 5xFAD, inhibiting the colony stimulating factor-1 receptor (CSF1R) markedly reduced microglial proliferation, rescuing synapse loss and cognitive deficits." (PMID 30863284, 2019). "We identified 3 likely pathogenic mutations in CSF1R TK domain (p.L868R, p.Q691H, and p.H703Y) in our discovery and validation cohort, composed of 465 AD and mild cognitive impairment (MCI) Caucasian patients from the United Kingdom." (PMID 29544907, 2018). "Using a clinically relevant model and pharmacologic approach, our data show that CSF-1R blockade by PLX5622 can prevent fWBI-induced cognitive deficits in mice by preventing loss of synaptic dendritic spines." (PMID 27576527, 2016). "In summary, the patient exhibits the core features of CSF1R-microglial encephalopathy: age of onset ≤60 years, cognitive impairment, autosomal dominant inheritance, bilateral symmetric deep white matter changes, brain atrophy (corpus callosum thinning), and a CSF1R gene mutation is present." (PMID 40893935, 2025). "In some cases, CSF-1R inhibition prevented or ameliorated cognitive deficits: fractionated whole brain radiation therapy caused deficits in hippocampal-dependent memory noted in novel object and matrix distance tests, which was ameliorated by a CSF-1R inhibitor-containing chow." (PMID 40760255, 2025). "Hereditary diffuse leukoencephalopathy with axonal spheroids (HDLS) is a rare autosomal dominant disease caused by mutations in the colony stimulating factor 1 receptor (CSF1R) gene that often results in cognitive impairment, psychiatric disorders, motor dysfunction and seizure." (PMID 31093799, 2019). "Moreover, recent studies have demonstrated that CSF1R mutation can affect brain structure (cerebral white matter change) and cause various brain dysfunctions, including early-onset cognitive impairment, behavioral changes, parkinsonism, seizures, and depression." (PMID 35721475, 2022). "Our study demonstrated that replenishing sCSF1R in Csf1r haploinsufficient mouse model of CRL can reverse reductions in synaptic scaffolding proteins and cognitive impairments in Csf1r+/− mice." (PMID 41350870, 2025). "Here, we found that sCSF1R alleviated cognitive impairment and anxiety-like behavior in Csf1r+/− mice." (PMID 41350870, 2025). "Some recent studies have further shown that inhibition of the CSF1R signaling pathway can alleviate cognitive impairment in multiple mouse models of neurodegeneration." (PMID 39695808, 2024). "Depletion of microglia prior to the onset of hypoperfusion using the CSF1R inhibitor PLX3397 reduces white matter damage and associated cognitive impairment." (PMID 37909242, 2024). "Overall, this work suggests that inhibition of CSF1R and microglial proliferation mediates protection against chronic cerebrovascular white matter pathology and cognitive deficits." (PMID 37909242, 2024). "Here, we provide encouraging exploratory evidence that CSF1R silencing dampened inflammation and prevented the progressive cognitive deficits due to stroke." (PMID 32345303, 2020). "In this present study we aim to decipher the contribution of microglia to hypertension-induced cognitive impairment via their depletion using a highly selective CSF1R tyrosine kinase inhibitor." (PMID 32863942, 2020).